PHGDH (phosphoglycerate dehydrogenase)
Diseases named in the same sentence as PHGDH in open-access papers (continued):
Sharing a sentence is not in itself a finding about the gene and the disease.
tumor (continued). "Mechanistically, PHGDH-mediated serine biosynthesis promotes α-ketoglutarate production, which activates mTORC1 signaling and contributes to the maintenance of an M2-like macrophage phenotype in the tumor microenvironment." (PMID 38409249, 2024). "Since tumour cells have exceptional metabolic preferences to meet survival and proliferation needs, it may be a viable therapeutic strategy to treat tumours with PHGDH overexpression by targeting specific enzymes, such as PHGDH19." (PMID 38577610, 2024). "Consequently, deletion of the PHGDH gene from endothelial cells inhibits the excessive growth of blood vessels, eradicates hypoxia within the tumor, and promotes the infiltration of T cells into the tumor." (PMID 38945960, 2024). "PHGDH interacts with the glycolytic enzyme phosphofructokinase 1 (PFK1), and the loss of this interaction activates HBP causing aberrantly enhances protein glycosylation thus promoting cell migration and tumor dissemination." (PMID 38115544, 2024). "Consequently, increased levels of ZEB1 and PHGDH are critical factors in both HCC tumor formation and the processes of migration and invasion." (PMID 38945960, 2024). "Notably, signals from the tumor microenvironment induce PHGDH expression in endothelial cells, activating a redox-dependent mechanism that leads to hyperproliferation of endothelial cells." (PMID 38945960, 2024). "Thus, distinguishing the specific contribution of PHGDH to TAM-mediated effects on tumor development is challenging." (PMID 38409249, 2024). "PHGDH is overexpressed in tumor cells and correlates with their aggressiveness and metastasis." (PMID 39207107, 2024). "As previously noted, NSCLC patient tumor samples showed higher expression of the different enzymes of the de novo ser/gly synthesis pathway, i.e. PHGDH, PSAT1, PSPH and SHMT2, compared to the adjacent normal lung tissue, which hardly showed any expression of ser/gly pathway enzymes." (PMID 38160212, 2024). "Based on the continuous discovery and improvement of PHGDH inhibitors, their effect in overcoming drug resistance or enhancing chemotherapy efficacy in tumour treatment may gradually become apparent." (PMID 38577610, 2024). "Moreover, PHGDH knockout abolished the proliferation-promoting effect of ASS1 knockout in vitro and in vivo, which indicated that the tumor suppressor function of ASS1 greatly depends on PHGDH." (PMID 38710705, 2024). "Overexpression or amplification of PHGDH has been observed in various tumor tissues." (PMID 38733440, 2024). "Recently, the role and function of PHGDH in tumor cells have been widely explored." (PMID 38733440, 2024). "It would be meaningful to investigate whether the inhibition of PHGDH alone or in combination with an mTORC1 inhibitor can elicit a promising antitumor response in patients whose tumor cells lack or express very low levels of PHGDH." (PMID 38409249, 2024). "Genetic ablation of PHGDH in macrophages from tumor-bearing mice results in attenuated tumor growth, reduced TAM infiltration, a phenotypic shift of M2-like TAMs toward an M1-like phenotype, downregulated PD-L1 expression and enhanced antitumor T-cell immunity." (PMID 38409249, 2024). "Interestingly, the CRC-cachectic potential is strongly related to PHGDH expression in tumor cells and exogenous Ser dependency, opening new possibilities for prognostic approaches." (PMID 39706853, 2024). "Similarly, the increase in tumor weight induced by ASS1 knockout was largely abrogated by further knockout of PHGDH." (PMID 38710705, 2024). "Based on above results that PKM2-IN-1 can accumulate 3-PG and upregulate PHGDH, we hypothesized that PKM2-IN-1 in combination with the PHGDH inhibitor may display a synergistic anti-tumor effect." (PMID 37284309, 2023). "Given that serine synthesis promotes tumor growth and survival, we next determined whether increased PHGDH activity favors the growth of HCC cells." (PMID 36823188, 2023).
tumor (continued). "In addition, the Knockdown or silencing of PHGDH showed significant antitumor effects in vitro and in vivo, indicating that PHGDH is a promising drug target for tumor therapy." (PMID 36803157, 2023). "In serine/glycine metabolism, tumor cells synthesize and utilize serine/glycine by a phosphoglycerate dehydrogenase (PHGDH)/phosphoserine aminotransferase 1 (PSAT1)/phosphoserine phosphatase (PSPH)/hydroxymethyltransferase (SHMT)-mediated continuous enzymatic reaction." (PMID 36778122, 2023). "The RNA and total protein levels of PHGDH were downregulated in tumor tissues." (PMID 37078828, 2023). "PHGDH may be associated with tumorigenic EMT through its association with The MAPK signaling pathway interacting with PI3K/AKT/mTOR signaling pathway may jointly promote tumor development, suggesting that PHGDH may act through different mechanisms." (PMID 36803157, 2023). "Moreover, PHGDH activity is directly related to enhanced tumor cell stemness by controlling the SRY-box transcription factor 2–OCT4 master complex of stemness in thyroid cancer." (PMID 37187454, 2023). "Importantly, PHGDH is highly expressed in CRC tumor tissues compared to normal tissues in TCGA‐COAD database and another two CRC datasets (TCGA‐COAD, GSE9348 and GSE41258)." (PMID 37544925, 2023). "We consistently found that total PHGDH was downregulated in tumor tissues." (PMID 37078828, 2023). "Moreover, PHGDH is a crucial enzyme in the serine synthesis pathway, and expression of this enzyme serve as a marker for tumor aggressiveness." (PMID 38111705, 2023). "Indeed, although frequently amplified in tumors, PHGDH overexpression is only beneficial to tumors when serine levels are limiting in the microenvironment of the tumor." (PMID 37949226, 2023). "Promisingly, NCT‐503, a PHGDH inhibitor, significantly repressed tumor growth in vivo (p = 0.0002)." (PMID 37387559, 2023). "Finally, we found a relative fold change in the expression of PHGDH of 7.40 in tumor vs. adjacent tissue and 1.37 in CTC vs. healthy donor tissue." (PMID 35805008, 2022). "Additionally, PHGDH was overexpressed in the vast majority of samples (9/10 (90%)),andthe difference between the tumor tissues (median = 6.23) and the adjacent tissues (median = 8.86) was statistically significant (p = 0.009)." (PMID 35805008, 2022). "We next evaluated the pharmacological activity of the PHGDH inhibitor PH-755 on tumor development." (PMID 35316216, 2022). "NCT-502, a PHGDH inhibitor, promotes ferroptosis and inhibits tumor progression in BCa." (PMID 36147463, 2022). "Interestingly, among these was PHGDH, the methylation of which was highly variable across tumor types." (PMID 35045283, 2022). "CBR-5884 is a PHGDH inhibitor that suppresses proliferation of PHGDH-dependent TNBC tumor cells." (PMID 36059650, 2022). "PHGDH-mediated serine synthesis plays a critical role in metastasis and tumor growth." (PMID 36144843, 2022). "We also examined the protein level of tumor tissues in two groups, which showed that PHGDH and pathway-related indicators β-catenin, c-myc, cyclin D1, PCNA, Bcl2, N-cadherin, vimentin, and Snail expression level were lower and BAX and E-cadherin higher in CBR-5884 group." (PMID 36105480, 2022). "Conversely, PHGDH silence can downregulate serine synthesis leading to tumor growth suppression." (PMID 35935878, 2022). "PHGDH could, therefore, be explored as a biomarker in other tumor types, as high expression may predict for treatment response." (PMID 33503424, 2021). "To determine the impact of serine/glycine limitation on circulating and tumour levels of hypoxanthine, we analysed serum and tumours from mice carrying DLD-1 xenograft tumours and treated with a serine/glycine-free diet in combination with the PHGDH inhibitor, PH755." (PMID 34702840, 2021). "Indeed, increased activity of D-3-phosphoglycerate dehydrogenase (PHGDH), the enzyme rate-limiting de novo serine synthesis, has been extensively reported in several tumours." (PMID 33931592, 2021).
tumor (continued). "In addition, IHC staining indicated that circ_0062682 knockdown reduced the expression of PHGDH and Ki67 in these tumor tissues." (PMID 34957102, 2021). "Indeed, several preclinical trials have proven that the targeted inhibition of PHGDH with small molecule inhibitors disrupts the serine synthesis pathway and restricts tumor growth and metastasis." (PMID 34957102, 2021). "Here, we demonstrated that PHGDH is a novel functional target of miR-940, and circ_0062682 could bind and inhibit miR-940, restoring the tumor-promoting activity of PHGDH in CRC." (PMID 34957102, 2021). "Accordingly, increased dietary serine and overexpressed PHGDH promoted tumor growth in mice." (PMID 33091721, 2020). "High PHGDH also contributes to tumor resistance to targeted therapy." (PMID 32226297, 2020). "Therefore, reducing PHGDH expression and blocking the binding of PHGDH to eIF4A1/eIF4E provides a new anti-tumor therapeutic design." (PMID 32226297, 2020). "Taken together, the high expression of PHGDH is dramatically related to tumor resistance to chemotherapies, and treatment with PHGDH inhibitor works synergistically with chemotherapy drugs and may be an effective approach to improve overall patient survival." (PMID 32226297, 2020). "Furthermore, combined treatment using a PHGDH inhibitor and gemcitabine/cisplatin achieved synergistic tumor suppression compared to use of a single agent both in vitro as well as in vivo." (PMID 32386122, 2020). "Many PHGDH inhibitors in the plasma are unstable and the anti-tumor mechanism of most parts of PHGDH remains unknown." (PMID 32226297, 2020). "Importantly, combined treatments using a PHGDH inhibitor and gemcitabine/cisplatin revealed synergistic inhibition of tumor growth compared to individual agents." (PMID 32386122, 2020). "However, in PHGDH knockdown cells, serine supplement can not completely rescue the cell proliferation, suggesting that the tumor-promoting function of PHGDH is not limited to amino acid synthesis." (PMID 30744688, 2019). "Clearly, PHGDH knockdown significantly impaired the tumor growth." (PMID 30744688, 2019). "Given the highly restricted PHGDH expression in 3D microtumors, it may be that PHGDH inhibitors alone may have a more limited effect on delaying tumor growth in patients than in combination with other antimetabolic therapies." (PMID 29925909, 2018). "In addition, PHGDH expression was found to correlate with tumour grade in glioma cells and tumour stage in cervical cancer." (PMID 29568346, 2018). "Moreover, three shRNA that scored in the in vivo screen also decreased PHGDH protein expression; two of differing knockdown efficacies inhibited tumor growth." (PMID 25574168, 2014). "In cells with established tumorigenic growth, doxycycline treatment of inducible shRNA reduced PHGDH protein levels in murine mammary fat pad tumors established with transduced MDA-MD-468 cells at 25 days, indicating that PHGDH suppression can adversely affect growth among established tumor cells." (PMID 25574168, 2014). "In addition to PHGDH, other glucose metabolism genes have also been shown to be more important for tumor initiation than tumor maintenance." (PMID 24318446, 2013). "One possible reason is that the reduction of metabolic products of PHGDH in vivo might be restored by other metabolism pathways when tumor sizes increase or tumors enter into later stages." (PMID 24318446, 2013). "Furthermore, phosphorylation of PHGDH by PLK1’s highly expression in tumor which includes both the tumor cells and tumor microenvironment cells amplified the effects on lipid synthesis, which might cause the enhanced fat production in the whole body of mice." (PMID 40475404, 2025). "However, inhibiting PHGDH may trigger compensatory mechanisms, such as increased extracellular serine uptake from the tumour microenvironment (TME)." (PMID 40660426, 2025).
tumor (continued). "In addition, nutrient deficiency results in the phosphorylation of PHGDH leading to its nuclear translocation which further represses the poly(ADP-ribosyl)ation of c-Jun by PARP1, thereby impairing c-Jun-mediated gene transcription for tumor growth." (PMID 40383841, 2025). "Studies have shown that exogenous serine supplementation does not restore cell growth inhibition caused by PHGDH knockdown, suggesting that PHGDH may have important nonmetabolic functions in tumour development." (PMID 38577610, 2024). "Moreover, depleting PHGDH significantly suppressed tumor metastasis." (PMID 38945960, 2024). "Taken together, these results indicate that PHGDH may be associated with TNBC recurrence, that its protein expression is downregulated by ASS1, and it is inversely associated with ASS1 expression in TNBC tumor tissue." (PMID 38710705, 2024). "However, abnormal PHGDH activation promotes tumor progression." (PMID 38733440, 2024). "Importantly, the tumor suppressive effects of ASS1 were strongly abrogated by PHGDH knockout." (PMID 38710705, 2024). "Moreover, depletion of PHGDH in the TNBC cell line Hs578T inhibited tumor growth." (PMID 37444501, 2023). "GSCs are also known to produce and secrete neurotransmitters such as histamine to establish a pro-angiogenic tumor microenvironment, and this aberrant angiogenesis may be reinforced by phosphoglycerate dehydrogenase (PHGDH)-mediated endothelial cell metabolism." (PMID 38132354, 2023). "To validate the relevance of our findings to human CRC and to examine whether hindering eIF3f‐PHGDH signaling axis can restrain the CRC tumor formation, we performed cell growth studies and the results showed that both NCT‐503 and LGK‐974 (Wnt inhibitor) could suppress CRC foci formation." (PMID 37544925, 2023). "The key enzyme of de novo serine synthesis pathway, PHGDH, is high-expressed for endogenous serine synthesis providing enough glycine and one-carbon units for nucleic acids biosynthesis and proteins expression to keep the continuous proliferation of tumor cells." (PMID 36185664, 2022). "Therefore, selective inhibition of PHGDH may represent a new therapeutic strategy for over-expressing PHGDH tumours, owing to its downstream inhibition of essential biomass production such as one-carbon units and nucleotides." (PMID 33931592, 2021). "Conversely, PHGDH overexpression in PHGDH-deficient GBM cell lines decreased invasion, suggesting that PHGDH may prolong patient survival by suppressing tumor invasion via its increased enzymatic activity." (PMID 32620753, 2020). "This discrepancy may be due to differences in tumor sizes used when assessing PHGDH knockdown." (PMID 24318446, 2013). "Overall, these findings demonstrate that PHGDH ablation impairs GSC proliferation and tumor progression." (PMID 40102981, 2025). "Consistent with cohort 1, the expression patterns of PHGDH, SLC1A5 and SLC38A2 in normal and tumour tissues from cohort 2 were identical for all three markers." (PMID 40660426, 2025). "In the serine synthesis pathway, key enzymes like PHGDH and PSPH are upregulated in specific tumor types." (PMID 40265021, 2025). "In vivo PHGDH expression was manipulated by injecting mice with GSCs expressing luciferase and DOX-induced PHGDH shRNA (Luc/DOX-shPHGDH), and DOX treatment upon tumor establishment drastically inhibited tumor growth and extended lifespan." (PMID 40102981, 2025). "In liver metastases, PHGDH and SLC38A2 were expressed in tumour cells, surrounding hepatocytes and bile duct cells." (PMID 40660426, 2025). "In CRC tissues, PHGDH, SLC1A5 and SLC38A2 were mainly expressed in tumour cells and the GCs of mature TLSs." (PMID 40660426, 2025). "ELISA assays confirmed that CXCL7 overexpression elevated SAM levels, and this effect was blocked by PHGDH inhibition, suggesting that CXCL7-induced serine metabolism in tumor cells mediates SAM secretion." (PMID 40368902, 2025).
tumor (continued). "Key enzymes for serine synthesis, such as phosphoglycerate dehydrogenase (PHGDH) and phosphoserine aminotransferase (PSAT), are often abnormally expressed in tumor cells." (PMID 40265021, 2025). "PHGDH ablation decreased SOX2 and Olig2 positive tumor cells in GBM xenografts, indicating a reduced GSC reservoir." (PMID 40102981, 2025). "PRMT1 significantly contributes to chemoresistance in TNBC by altering the methylation of key molecules like epidermal growth factor receptor (EGFR) and phosphoglycerate dehydrogenase (PHGDH), which strengthens tumor resilience." (PMID 40927753, 2025). "The results showed that RFWD3 knockout significantly increased PHGDH expression, reduced the NAD+/NADH ratio, and elevated serine levels of the subcutaneous tumor." (PMID 40019400, 2025). "Further investigations revealed that circSIRT5 promotes the ubiquitination and degradation of PHGDH by forming the circSIRT5/SYVN1/PHGDH ternary complex, thereby facilitating ferroptosis in BC cells and acting as a tumor suppressor." (PMID 39223162, 2024). "Our study provides a strong basis for further exploration of PHGDH as a potential target to counteract TAM-mediated immunosuppression and hinder tumor progression." (PMID 38409249, 2024). "This augmentation of PHGDH activity boosts serine production, mitigates oxidative stress, and eventually promotes HCC cell proliferation and tumor growth." (PMID 38997696, 2024). "Mechanistically, circSIRT5 exerted its tumor-suppressive activities through the formation of a ternary complex involving circSIRT5, SYVN1, and PHGDH." (PMID 39223162, 2024). "The attenuation of tumor growth and simultaneous reduction in TAM infiltration prompted us to assess the influence of PHGDH depletion in macrophages on the crosstalk of TAMs with tumor cells." (PMID 38409249, 2024). "In CRC patient tissues, immunohistochemical analysis has consistently shown that PHGDH displays heightened expression levels that positively correlate with both TNM stage and tumor size." (PMID 38945960, 2024). "The expression levels of PHGDH and ASRGL1 were significantly correlated with four or more clinicopathologic features (stage, grade, LNM, peritoneal cytology, tumor state, and survival status)." (PMID 37387559, 2023). "For example, metabolomic and transcriptomic analyses of human and mouse GBM showed that the expression of phosphoglycerate dehydrogenase (PHGDH) and serine metabolism were significantly altered in tumor endothelial cells." (PMID 38111705, 2023). "Here, it is demonstrated that eIF3f is upregulated in CRC tumor tissues and that both Wnt and EGF signaling pathways are participating in eIF3f's oncogenic impact on targeting phosphoglycerate dehydrogenase (PHGDH) during CRC development." (PMID 37544925, 2023). "For small molecule inhibitors that inhibit PHGDH (for example, NCT-503, CBR-5884), the tumor has to be fully addicted to PHGDH." (PMID 37627515, 2023). "Significantly, administration of the PHGDH inhibitor NCT‐503 in the established eIF3f high PDX tumors (CRC#116, 216) attenuated tumor growth; while NCT‐503 had little impact on the growth of eIF3f low PDX tumors (CRC#309, 490)." (PMID 37544925, 2023). "The results revealed that PHGDH and NR1I2 genes exhibited low expression in HCC tumor tissues (P-value < 0.001) while APOC2 genes were highly expressed in HCC tumor tissues (P-value < 0.01)." (PMID 37008043, 2022). "With the promising in vitro data, we examined the combinatorial effect of PHGDH modulation and radiation in HCT116 tumor-bearing mice in a preliminary experiment." (PMID 36291844, 2022). "Based on the results of qRT-PCR and the immunohistochemical analyses of the cell lines and the FFPE tissues from the synchronous collision tumor, we finally identified two novel MPM marker genes, PHGDH and TRIM29." (PMID 35204409, 2022).